CDK4 (cyclin dependent kinase 4)
Diseases named in the same sentence as CDK4 in open-access papers (continued):
Sharing a sentence is not in itself a finding about the gene and the disease.
tumor (continued). "Since CDK4/6 inhibitors induce, in addition to a tumor cell cycle arrest, an enhanced antitumor immune response, they may be used in synergy with ICI to increase tumor immunogenicity (NCT02648477)." (PMID 38433837, 2024). "Overall, the differences we found in the tumor genomic landscape suggest that treatment strategies and the development of new therapeutics for advanced HR+/HER2- BC may need to be adapted for patients previously treated with CDK4/6i." (PMID 38388477, 2024). "Furthermore, clinical research using CDK4/6 inhibitors not only confirmed our original MASH findings but also provided insight into the function and mode of macrophage E2F2 signaling in the context of anti‐tumor immunity." (PMID 39465673, 2024). "Second, although preclinical data has shown that CDK4/6 inhibitors can stimulate immune-related effects, this has not been well-studied in patients or within different tumor intrinsic subtypes, and the early disease setting represents the perfect context to evaluate this phenomenon." (PMID 38448600, 2024). "In RB1 proficient tumours with elevated E2F expression, it may not be sufficient to target Cdk4/6 with Palbociclib but also target the E2fs." (PMID 37606819, 2024). "The combined use of PRKDC and CDK4 inhibitors most significantly decreased the proliferation of PDC_PRKDCAmp&CDK4Amp cells, demonstrating that PRKDC could enhance the ability of CDK4 to promote tumor cell proliferation in the S-III subtype." (PMID 39039072, 2024). "The immunoexpression of IMP3 was observed in 21 of 92 (22.82 %) cases, CDK4 in 13 of 94 (13.82 %) cases, MDM2 in 17 of 99 (17.17 %) cases, and β-catenin in 8 of 90 (8.8 %) cases, with no significance for percentage of positive cells between the analyzed tumor's group." (PMID 39368400, 2024). "Finally, the effects of CDK4/6i exposure are still observed in later line samples, suggesting that CDK4/6i treatment may have a lasting effect on the HR+/HER2- tumor genomic profile." (PMID 38388477, 2024). "Two samples with no CDK4 phosphorylation (E8, L7) were not proliferative and stained positive for p16, indicating that these tumour samples could be in a senescent state." (PMID 36453028, 2024). "As the inhibitors did not cause a full tumor regression, the researchers performed RNA sequencing, which revealed upregulation of the oxidative phosphorylation (OxPhos) pathway in UM resistant to MEKI and tolerant of the CDK4/6 inhibitor." (PMID 39598629, 2024). "The tumor tissues were then analyzed by Western blotting to detect the different expression levels of proliferation (Ki67 and PCNA), apoptosis (c-Casp3, c-PARP), metastasis (vimentin), related substrate (p-PDH, HDAC1), and cell cycle-related proteins (CDC25A, CDK4, CDK6, and Rb) in each group." (PMID 38948069, 2024). "This confirms that prolonged CDK2 inhibition in vivo can exert sustained control of CCNE1-amplified tumors, and that rebound compensation by CDK4/6 is not present to a level sufficient to significantly restore Rb phosphorylation, cyclin A2 expression, or tumor growth." (PMID 38047585, 2024). "In addition to its important role in the cell cycle, CDK4 exerts immunomodulatory and immunogenic effects by negatively interfering in the expression of PD-L1 in tumor cells and also in the direct reduction of infiltrating T lymphocytes of the immune system." (PMID 39368400, 2024). "Similarly, neoplasms with GLI1 amplification and coamplification of MDM2/CDK4 could benefit from MDM2/CDK4 inhibitors." (PMID 38275873, 2024). "Preclinical studies suggest that although proliferation of these tumors is primarily CDK4/6-dependent, resistance to CDK4/6i monotherapy might be driven by CDK2 activity, and clinical data has shown a correlation between high tumor CCNE1 mRNA levels and impaired response to combined CDK4/6i +/- ET." (PMID 38047585, 2024). "However, CDK4 can also promote tumor growth through mechanisms that are independent of the Rb pathway." (PMID 39723387, 2024).
tumor (continued). "For example, the use of CDK4/6 inhibitors in melanoma cells can induce the secretion of tumor cells through CCL5, which relies on the NF-κB signal and promotes the recruitment of tumor-infiltrating leukocytes, which is the result of stimulating antitumor immunity." (PMID 38540708, 2024). "Therefore, concomitant alterations in multiple oncogenic pathways were most common in tumor samples after CDK4/6i exposure compared with samples without CDK4/6i exposure." (PMID 38388477, 2024). "Moreover, a combination of mTOR and CDK4/6 inhibitors may prevent pathway reactivation downstream of PI3K, interfering with the survival of resistant cells and consequent tumor escape." (PMID 36792625, 2023). "Monitoring circulating tumor DNA (ctDNA) has been shown to detect disease progression well in advance of radiological assessment in both patients responding and not responding to CDK4/6i." (PMID 37366894, 2023). "Moreover, the latest studies have revealed that CDK4/6 inhibitors may stimulate the immune system, namely, CD8 T-cell immune memory cells, interact with the tumor microenvironment, and have antitumor immunity effects." (PMID 37886029, 2023). "However, the tumor tissues in the GAA treatment group and the combination group showed lower levels of LRPPRC and CDK6 than the control group and CDK4/6i monotherapy group, suggesting that the addition of GAA can also block the LRPPRC-CDK6 feedback loop in vivo." (PMID 37452037, 2023). "Furthermore, the expression of N-Cadherin, MMP2, CDK4, and cyclinD1 was significantly elevated, and E-cadherin was inhibited in ccRCC cells that knocked down HOXD3, suggesting a tumor-suppressive role for HOXD3 in KIRC tumor." (PMID 37827698, 2023). "We show that CDK4/6 inhibitor resistance following long-term exposure to palbociclib has the potential to upregulate PI3K-AKT signalling, downregulate ER pathways, and influence subsequent effects of both AKT and ER inhibition on tumour cell signalling and function." (PMID 37543694, 2023). "Thus, we speculated that CDKN2A rs3088440 might up-regulate the expression of PD-L1 through CDK4, hence inducing CD8+ T lymphocytes depletion and ultimately leading to tumor cell proliferation and metastasis." (PMID 37314514, 2023). "RB1, ERBB2, and CCNE1 alterations were noted in patients who were not responsive to abemaciclib, suggesting that tumor biomarkers may help in the selection of patients who will respond to a rechallenge to a CDK4/6i." (PMID 36980743, 2023). "Additionally, CDK4 OE could promote the growth of PHF6 KD HEC‐1‐A cells, suggesting that PHF6 might regulate the tumour growth through CDK4 signalling pathway." (PMID 36756714, 2023). "Therefore, we assumed that the knockdown of CCND1b downregulated the ratio of CCND1b/a, inhibited the CDK4/CyclinD1‐pRB‐E2F1 signalling pathway, prevented tumour cells from passing through the G1‐S transition, resulting in cycle arrest, thereby decreasing the chemoresistance of MCF‐7/ADM cells." (PMID 36915230, 2023). "In preclinical analyses evaluating potential factors contributing to tumor growth in VHL-null Drosophila and human clear cell RCC, synthetic lethality was discovered between the decreased activity of cyclin-dependent kinases 4 and 6 (CDK4/6) and VHL inactivation." (PMID 36980956, 2023). "Taken together, our data suggest that the global activation of the PI3K/AKT/mTOR signaling axis in tumors with short-term/lack of response to CDK4/6 inhibition in combination with ET extends beyond the tumor compartment into the surrounding tumor microenvironment." (PMID 36797347, 2023). "Therefore, the combination of capivasertib and fulvestrant reduces tumour growth in tumours that are CDK4/6 inhibitor resistant or have been exposed to CDK4/6 inhibitor long term and has efficacy in tumours without mutations in the PI3K-AKT pathway." (PMID 37543694, 2023).
tumor (continued). "If the host’s immune status may be well maintained and tumor cells are scarce, the treatment strategies aiming for a cure with CDK4/6 inhibitors or immune-related agents, rather than cytotoxic agents, should be considered an option." (PMID 37158934, 2023). "High proliferation rates have been related to nonspecific sensitization to cytotoxic agents; interestingly, neither CDK4 nor filamin A overexpression sensitized tumour cells to the other cytotoxics received in the neoadjuvant TNBC setting (anthracyclines or platins)." (PMID 36477027, 2022). "MDM2 analysis could not be performed but CDK4 was overexpressed in both tumor components, confirming the sarcomatous nature of each and ruling out metaplasia of the fatty component." (PMID 35384584, 2022). "One of these studies was also designed to test the utility of CDK4 expression in predicting tumour response to CDK inhibitors, but this study did not evaluate whether patients show loss of p16INK4A or intact Rb." (PMID 34921235, 2022). "There is evidence to suggest that CDK4/6i can increase tumor cell sensitivity to proton therapy through impaired RAD51 foci formation, but at present, our understanding of the relationship between simultaneous radiation treatment and CDK4/6 inhibitor therapy in the treatment of TNBC is insufficient." (PMID 34932500, 2022). "Interestingly, regardless of RB1 status, CDK4/6 inhibitors increase PD-L1 expression on tumor cells by decreasing its rate of degradation." (PMID 35911672, 2022). "In addition, co-targeting FGFR4 and CDK4/6 could significantly inhibit FGF19-driven LUSC proliferation and tumor growth in vitro and in mouse models." (PMID 35463335, 2022). "In our case, the tumor cells were diffusely positive for CDK4 but negative for MDM2." (PMID 34089125, 2022). "Further, this effect may be seen even in tumors intrinsically resistant to CDK4/6 inhibitors, as their effect on PD-L1 expression is independent of RB-status in tumor cells." (PMID 35911672, 2022). "As such, balancing the anti-proliferative effects of CDK4/6i on both tumors and lymphocytes in a way that induces tumor cell cytostasis, without compromising anti-tumor T cell immunity, will be important to maximize the clinical activity of CDK4/6i+ICI combinations." (PMID 35444175, 2022). "A comparative genomic hybridization array analysis of the primary tumor from a 27-year-old patient with relapsed and chemotherapy-refractory ARMS identified the highest level of amplification in the 12q13–14 region—more specifically, CDK4 was highly amplified in this region." (PMID 35892870, 2022). "FISH analysis revealed that the tumor was negative for MDM2/CDK4/FRS2 amplification." (PMID 36059611, 2022). "Given the role that cyclin D:CDK4/6 plays in cell cycle reentry from senescence, it is conceivable that sequential treatment with a DNA‐damaging agent followed by an FDA‐approved CDK4/6 inhibitor such as palbociclib might help reduce tumor recurrence." (PMID 36161508, 2022). "The convergence of CDK4/6 and AKT-regulated processes on key hallmarks of cancer strongly supports the idea that the coordinated modulation of both pathways could additively or synergistically inhibit tumor progression." (PMID 35158840, 2022). "This could be explained by the increased activation of CDK2 in the process of palbociclib resistance, and tumor metabolism not completely reflecting the true condition of CDK4/6." (PMID 35711853, 2022). "Univariate analyses revealed that age, tumor location, depth and size, thick septa (> 2 mm), enhancement of septa or nodular lesions, histological findings excluding the proliferation of fibrous septa, and FISH examination for MDM2 and/or CDK4 were significantly different." (PMID 34997060, 2022).
tumor (continued). "After adjusting tumor stage and radical resection, the multivariate Cox regression model of TCGA cohort suggested that high expression of CDK1 (adjusted HR = 1.541; adjusted P = 0.028) and CDK4 (adjusted HR = 1.721; adjusted P = 0.005) were statistically related to OS." (PMID 35193513, 2022). "However, in their study, the metabolic response by FDG‐PET has not correlated with tumor proliferation and CDK4/6 inhibition in some patients whose resistance to palbociclib occurs within several months." (PMID 35711853, 2022). "Based on the identification and understanding of the cyclin-dependent kinase 4 (CDK4) and CDK6, the activator such as cyclin D1, and their multiple cyclin inhibitors, the concept of an inhibitor for cell cycle kinases to block cell cycle progression and tumor growth seems obvious." (PMID 36185294, 2022). "In addition, inhibiting CDK4/6 could also promote cytotoxic T-cell-mediated immunity against tumor cells by stimulating type III interferon production, thus enhancing tumor antigen presentation." (PMID 33435254, 2021). "Importantly, switching from fulvestrant and CDK4/6i combination, upon resistance, to the combination of AKTi and fulvestrant did not prevent tumor progression." (PMID 34433817, 2021). "However, in line with the multiple activities of CDK4 and CDK6, it is highly expected that the use and the success of CDK4/6i will be also related to many other alterations, present both in tumor cells and in tumor microenvironment." (PMID 34204543, 2021). "The potential need for combined inhibition of CDK4 and CDK6 kinase activities represents another possibility that might explain why T cell-intrinsic CDK6-deficiency does not have an impact on anti-tumor immunity." (PMID 34248938, 2021). "Besides CDK4, CDK2 is highly expressed in the tumor tissues of STSs." (PMID 33686022, 2021). "Because the clinical benefit of CDK4/6 or PARP-1 targeted inhibition as respective monotherapies might be, as also shown in other tumor entities, limited for BLCA, suitable combination therapies for these compounds are necessary for sufficient therapeutic efficiency." (PMID 33923231, 2021). "Genomic alterations on circulating tumor DNA and serum thymidine kinase activity, but also circulating tumor cells, epigenetic or exosome markers are currently being tested as markers of CDK4/6i treatment response, even though none of these have been integrated into clinical practice." (PMID 34072070, 2021). "Finally, in triple-negative breast cancer (TNBC), an increased number of tumor cell lysosomes has been shown to mediate the intrinsic resistance to CDK4/6 inhibition." (PMID 33535617, 2021). "Interestingly, tumor immunogenicity in response to CDK4/6i is not attributable to the induction of senescence." (PMID 34025662, 2021). "In addition to CDK4 and CDK5, cyclin-B/CDK1 may play a role in tumor cell spreading, motility, and invasion." (PMID 33723248, 2021). "Similarly, YTHDF1 deficiency could inhibit NSCLC cell proliferation and xenograft tumor formation by regulating the translational efficiency of cell-cycle-related genes, such as CDK2, CDK4, and cyclin D1." (PMID 34359836, 2021). "Consequently, with frequent liquid biopsies, the detection of mutant KRAS in circulating tumor cells can help clinicians determine who will not respond to palbociclib, and likely, the other two CDK4/6 inhibitors." (PMID 34830174, 2021). "As an oncogene, CCND1 was shown to promote tumor growth by regulating cyclin-dependent kinase 4 (CDK4), through modulating the cell cycle transtion from the G1 to the S phase, thereby making CCND1 and its regulatory partner, CDK4, attractive potential therapeutic targets." (PMID 34063946, 2021). "Moreover, there were no marked differences in gene expression of key tumor cell division (p27, CDK4 and Hes1) and inflammation markers (F4/80 and IL-6) following metformin treatment." (PMID 34829914, 2021).
tumor (continued). "Thus, the mechanism enabling the bypassing of G1 checkpoint without CDK4/6 in these tumor cells including HCC, as well as the non-canonical function of CDK4/6 needs to be elucidated." (PMID 34335925, 2021). "Importantly, switching from combined fulvestrant and CDK4/6i upon resistance to dual combination with AKTi and fulvestrant does not prevent tumor progression." (PMID 34433817, 2021). "In a previous biomarker analysis of tumor tissues from PALOMA-2, no predictive biomarker was associated with lack of benefit from palbociclib plus letrozole treatment, but higher CDK4 expression was identified as a marker of resistance to treatment with letrozole alone." (PMID 32783178, 2020). "Previous reports also showed that CCNE2 could drive tumour cell proliferation by activating its kinase partner CDK2,47, 48 but whether CCNE2 could directly regulate CDK4 was still unclear or CCNE2 affect the expression of CDK4 via an indirect manner." (PMID 32141702, 2020). "Moreover, we demonstrated that cytoplasmic p16 interacted with CDK4 and other unreported proteins, such as BANF1, AKAP8 and AGTRAP, which could sequester p16 to avoid nuclear translocation, and then, impair its anti-tumor function." (PMID 32204550, 2020). "Therefore, if abemaciclib treatment alone is not enough to decrease tumor volume, a combination of CDK4/6 inhibitors with chemotherapy or radiotherapy is essential." (PMID 33271970, 2020). "Our results show that the three tumours responding to volasertib are partially responsive to palbociclib and PDX with primary resistance to palbociclib were also resistant to volasertib, suggesting that cell cycle is the common determinant of response to CDK4/6 and PLK1 inhibitors." (PMID 32792481, 2020). "Finally, the TROJAN-NKRF complex upregulated the transcription of CDK2, a noncanonical cell cycle S-phase entry pathway that allows tumor cells to escape after CDK4/6 inhibition." (PMID 32393270, 2020). "It has been argued that the addition of CDK4/6 inhibitors to ET may not produce relevant benefits for less aggressive tumours, namely, tumours with bone-only metastases or long TFI or limited number of metastases." (PMID 32899139, 2020). "Trials that combine the CDK4/6 inhibitors with various PI3K/AKT/mTOR inhibitors (ClinicalTrials.gov Identifiers: NCT03128619, NCT03006172, NCT02684032, NCT02732119, NCT02871791, NCT02599714) are ongoing, with the aim to inhibit tumor growth and prevent relapse." (PMID 31178825, 2019). "Furthermore, tumor angiogenesis was found to be dysregulated by interference of miR-34a with VEGF secretion in tumor cells, as well as EC proliferation, migration, and tube formation, by downregulating a number of key proteins including E2F3, SIRT1, survivin, and CDK4." (PMID 30717449, 2019). "This suggests, that despite ER-driven tumor growth being maintained in a post-CDK4/6i setting, not all ER antagonists may be able to effectively inhibit growth." (PMID 31852484, 2019). "Moreover, by analysing the GSE37364 datasets, we found that cyclin D1, CDK4, and Twist1 were significantly up-regulated in CRC tissues, whereas E-cadherin was significantly down-regulated in CRC tissues when compared with the non-tumour tissues (all p < 0.05)." (PMID 31772673, 2019). "Therefore, the potential nonresponder type (type 0) was defined by either p16 expression in over 10% of the tumour cells, lack of the p-Rb molecule, or the absence of both CDK4 and CDK6." (PMID 30804704, 2019). "Therefore, we hypothesised that the suppression of tumour growth of GC by RN181 may undergo by reducing the expression and assembly of cyclin D1 with CDK4 mediated by inhibition of ERK/MAPK signalling in the stomach." (PMID 30714150, 2019). "Therefore, ER positivity of the tumor specimen is not sufficient to predict the response of CDK4/6 inhibitors." (PMID 29963233, 2018).